INS (insulin)
Diseases named in the same sentence as INS in open-access papers (continued):
Sharing a sentence is not in itself a finding about the gene and the disease.
type 2 diabetes (continued). "In individuals with adult-onset diabetes, presence of N-terminally truncated GAD65 autoantibodies is associated with the clinical phenotype of autoimmune type 1 diabetes and predicts insulin therapy." (PMID 29619531, 2018). "In a large previous study in Brazil, from the 5750 patients with Type 2 diabetes, 35% injected insulin and 58% of those did 2 injections/day." (PMID 30498521, 2018). "In five out of the six studies, participants had previously diagnosed Type 2 diabetes, who already received treatment (mostly insulin)." (PMID 30475888, 2018). "In type 2 diabetes patients, metformin reduces hyperglycemia and increases insulin sensitivity by enhancing insulin-stimulated glucose uptake in muscles, liver, and adipose tissue and by reducing glucose output by the liver." (PMID 30147674, 2018). "Type 2 diabetes is designated by a chronic progressive course and a subsequent need for a long-term insulin therapy to achieve optimal glucose control." (PMID 29563974, 2018). "It has been suggested that about half of the insulin treated patients with type 2 diabetes tend to have monthly physician visits, likely due to high frequency of complications." (PMID 29682315, 2018). "An insulin secretagogue function was ascribed to GS following observations that its administration led to elevations in serum insulin levels in individuals with type 2 diabetes." (PMID 30158997, 2018). "Insulin degludec/insulin aspart versus biphasic insulin aspart 30 in Asian patients with type 2 diabetes inadequately controlled on basal or pre-/self-mixed insulin: a 26-week, randomised, treat-to-target trial." (PMID 29527102, 2018). "As expected, GADA-positive individuals were diagnosed at a younger age and with a lower BMI, lower triacylglycerols and higher HDL-cholesterol, and were more likely to progress to insulin than were individuals with type 2 diabetes." (PMID 29260253, 2018). "Via activation of ATM, long-term treatment of CQ protects against atherosclerosis, improves insulin sensitivity, and rescues glucose tolerance in type 2 diabetes (T2D)." (PMID 29717979, 2018). "Further studies are needed to understand how exercise changes liver fat and hepatic insulin sensitivity in relation to energy balance and macronutrient intake among individuals with obesity and type 2 diabetes." (PMID 29696296, 2018). "Type 2 diabetes develops from both the insulin resistance of peripheral tissues and dysregulation of the endocrine function of pancreatic islets-impairments in insulin release from pancreatic β-cells and greater glucagon secretion from pancreatic α-cells." (PMID 30050001, 2018). "Low-dose STZ induces a mild impairment of insulin secretion similar to the characteristics of later-stage type 2 diabetes." (PMID 29721029, 2018). "Protein tyrosine phosphatase 1B (PTP1B) is a validated therapeutic target for Type 2 diabetes due to its specific role as a negative regulator of insulin signaling pathways." (PMID 29912965, 2018). "Sitagliptin increased DPP4 expression in skeletal muscle, which seems counterintuitive since high local DPP4 levels are thought to impair insulin signalling and thereby induce/deteriorate the development of type 2 diabetes." (PMID 30145664, 2018). "Some of the effects of coffee involved in the prevention of type 2 diabetes includes: improvement of glucose tolerance, insulin sensitivity and insulin secretion, reduction of glucose intestinal uptake and regulation of glucose metabolism." (PMID 29300317, 2018). "PPARγ is an evolutionary conserved transcription factor belonging to the nuclear hormone receptor superfamily that plays important roles in adipogenesis and insulin sensitivity, type 2 diabetes, atherosclerosis, and cancer." (PMID 30563100, 2018). "For comparison, the expected frequency of severe hypoglycemia in insulin users with type 2 diabetes is 4–5 events per 100 patient years." (PMID 29682315, 2018).
type 2 diabetes (continued). "Kovil R, Chawla M, Rajput R, Singh AK, Sinha B, Ghosal S, Ballani P, Gupta S, Tanna S, Bandukwala SM, Shah T. Consensus on insulin dose and titration algorithms in ambulatory care of type 2 diabetes in India." (PMID 29527102, 2018). "In the current study, the IFG and type 2 diabetes patients showed steady increases in fasting serum glucose, insulin, HbA1c, and HOMA-IR across the wGRS groups." (PMID 29777116, 2018). "Regarding diabetes-related researches, α-mangostin was found to improve glucose uptake by 3T3-L1 adipocytes, exert antihyperglycemic activity, and improve insulin insensitivity in type 2 diabetic rats induced by streptozotocin (STZ)." (PMID 29772703, 2018). "This is a randomized double-blind multi-center clinical trial of insulin plus metformin versus insulin plus placebo for the treatment of type 2 diabetes complicating pregnancy." (PMID 30541506, 2018). "Studies show that pancreatic function is deranged in critically ill patients displaying similarities to type 2 diabetes, namely insufficient insulin secretion in a context of decreased insulin sensitivity." (PMID 30071851, 2018). "An early study of insulin-treated type 2 diabetes patients, reported that a VLED approach resulted in significant weight loss and cessation of insulin in some patients." (PMID 29784059, 2018). "We had limited power to study differences of tumor protein expression among insulin users in women with type 1 and type 2 diabetes and between insulin analogues users and human insulin only users." (PMID 29486734, 2018). "The group with type 1 diabetes had a lower BMI, was diagnosed at a younger age, and progressed to insulin more rapidly than the group with type 2 diabetes." (PMID 29199115, 2018). "To this end, we used a mouse model in which Lkb1 was deleted selectively in β cells, mimicking, at least in part, changes during early development, pregnancy, and insulin resistance (“compensation”) prior to the onset of type 2 diabetes." (PMID 29967064, 2018). "It has been reported that consumption of a bilberry extract containing 36% (w/w) anthocyanins, reduced both postprandial glycemic and insulin responses in the individuals with type 2 diabetes." (PMID 29486772, 2018). "Misra A, Alappan NK, Vikram NK, Goel K, Gupta N, Mittal K, Bhatt S, Luthra K. Effect of supervised progressive resistance-exercise training protocol on insulin sensitivity, glycemia, lipids, and body composition in Asian Indians with type 2 diabetes." (PMID 29527102, 2018). "The aim of this study was to assess the size and shape of the associations of FPG, 2hPG, HbA1c, fasting insulin, and HOMA-IR with incident type 2 diabetes." (PMID 29018885, 2018). "A global rise in the incidence of type 2 diabetes coupled with improved access to insulin treatment and longer life expectancies means that the management of hypoglycaemia in type 2 diabetes is becoming increasingly important." (PMID 28660491, 2018). "Daily insulin doses and injection frequencies of neutral protamine Hagedorn (NPH) insulin, insulin detemir and insulin glargine in type 1 and type 2 diabetes: a multicenter analysis of 51,964 patients from the German/Austrian DPV‐wiss database." (PMID 29527102, 2018). "This review focuses on the effects of EH and soy hydrolysate (SH) or peptides in improving or preventing type 2 diabetes (T2D) and obesity in vivo or relevant in vitro endpoints such as insulin signaling pathways." (PMID 29710777, 2018). "In general, the management of diabetes involves three main aspects: reduction in blood glucose, preservation of beta cells, and, in the case of type 2 diabetes, improvement of insulin action." (PMID 30510749, 2018). "miR-27a-3p and miRNA-29 family members are possible regulators of peripheral insulin sensitivity and are found to be upregulated in skeletal muscles of human type 2 diabetic patients than normal obese/overweight individuals." (PMID 29770126, 2018).
type 2 diabetes (continued). "Positive effects have been described for these proteins on blood pressure, risk of cardiovascular disease and the prevention and treatment of type 2 diabetes, by modulating the insulin signaling pathway and diminishing inflammation." (PMID 30369937, 2018). "Late diabetes type 2 is characterized by long persistence of high postprandial plasma glucose levels, reduced insulin levels (hypo-insulinemia) and elevated glucagon levels (hyper-glucagonemia)." (PMID 30631280, 2018). "As type 2 diabetes (T2D) progresses, administering basal and bolus insulin through multiple daily injections (MDI) is often required to achieve target control, although many people fail to achieve target levels." (PMID 32685574, 2018). "The results of the First Basal Insulin Evaluation Asia study in 2015 compared the use of insulin therapy and oral hypoglycemic agents, HbA1c levels, and comorbidities in patients with type 2 diabetes in Asian countries." (PMID 30143020, 2018). "We conducted a randomized, placebo-controlled trial to evaluate the effect of one dose of intranasal insulin (40 IU of regular insulin) or saline on LH concentrations in 14 men (8 with type 2 diabetes and 6 healthy lean men)." (PMID 30515210, 2018). "This study included patients treated with the full spectrum of non-insulin injectable medications for type 2 diabetes that were available at the time of data collection, including all GLP-1 RAs and pramlintide." (PMID 30294713, 2018). "Consequent to this, the raised pancreas fat content falls and in early type 2 diabetes, normal first-phase insulin secretion becomes re-established with normal plasma glucose control." (PMID 29143063, 2018). "A previous study of basal insulin monotherapy versus CSII for early intensive treatment of type 2 diabetes reported greater glycemic excursions with basal insulin compared with CSII." (PMID 30420969, 2018). "In clinical and observational studies, these brief questionnaires can complement measures of treatment efficacy and provide a more thorough picture of patients’ experiences with non-insulin injectable treatments for type 2 diabetes." (PMID 30294714, 2018). "In this context, PPARγ is the target of thiazolidinediones (TZD), a class of antidiabetic drugs, that improve insulin sensitization and regulate glycemia in type 2 diabetes." (PMID 29449830, 2018). "This topic has been addressed in a number of randomised controlled trials that have evaluated the administration of DPPIVi in previously DPPIVi-naïve patients with type 2 diabetes who were poorly controlled on basal insulin therapy." (PMID 29370218, 2018). "This receptor is the target of thiazolidinediones, a class of antidiabetic drugs, which improve insulin sensitization and regulate glycemia in type 2 diabetes." (PMID 29449830, 2018). "Although AICAR treatment represents a promising strategy to improve muscle insulin sensitivity in type 2 diabetes, observations in humans have so far been inconclusive, given its relatively high threshold for AMPK activation in skeletal muscle." (PMID 29242278, 2018). "RELA can suppress inflammation and improve insulin sensitivity, which significantly regulate type I and type II diabetes.MiR-101a can promote inflammatory cytokine-mediated beta-cell dysfunction to regulate the development and progression of type I diabetes." (PMID 30521536, 2018). "Individuals with normal weight and normal glucose tolerance are highly sensitive to insulin in skeletal muscle, adipose tissue and liver, whereas obese individuals and individuals with type 2 diabetes are insulin resistant." (PMID 29535167, 2018). "A multicentre RCT is currently assessing the addition of metformin to insulin in pregnant women with type 2 diabetes." (PMID 29973490, 2018). "Gallwitz B. The future of combination therapies of insulin with a glucagon-like peptide-1 receptor agonists in type 2 diabetes—is it advantageous?" (PMID 29527102, 2018).
type 2 diabetes (continued). "In the study with diabetes type II, threshold values were determined depending on other predictors of hospitalization (such as prior hospitalization, number of monthly prescriptions, insulin use), and ranged from 46 to 92%." (PMID 30524276, 2018). "In certain physiological conditions like type 2 diabetes, differential selection of substrate fuel shows greater rate of fatty acid oxidation and insulin resistance." (PMID 29962969, 2018). "In type 2 diabetes, pancreatic β-cells are required to secrete increasing amounts of insulin to compensate for increasing insulin resistance." (PMID 30510621, 2018). "Cidea is also reported to be markedly up-regulated in ob/ob mouse livers, and its expression is induced by insulin in type 2 diabetic mouse livers." (PMID 29352167, 2018). "Regular cocoa consumption has been shown to improve blood pressure (BP), insulin sensitivity, and lipid levels in patients with type 2 diabetes (T2D), using up to 100 g of chocolate or 54 g of cocoa." (PMID 30301127, 2018). "Another ongoing study is examining the impact of an LED approach on type 2 diabetes patients who are on insulin treatment (ISRCTN2133588)." (PMID 29784059, 2018). "Beside the presence of the metabolic syndrome and type 2 diabetes and fasting serum insulin, raised AST levels and AST/ALT ratio are often used as independent predictors of liver fat and NAFLD." (PMID 30510710, 2018). "Type 2 diabetes is characterized by insulin resistance, and in earlier stages by hyperinsulinemia (high levels of endogenous insulin)." (PMID 29486734, 2018). "Approximately 70% of patients with type 2 diabetes were on treatment (50% on insulin and 50% on either sulphonylureas or metformin or a combination), however, we were unable to stratify them." (PMID 29924824, 2018). "IRS can be inhibited by S6K resulting in insulin-resistance thereby promoting the development of diabetes mellitus type II." (PMID 29596489, 2018). "The study included 162 type 2 diabetic patients divided into three groups (insulin taking group (N=58), glibenclamide taking group (N=40), and metformin taking group (N=64), and 47 normal healthy controls." (PMID 30349765, 2018). "This study suggests clinical inertia exists in basal insulin-treated patients with type 2 diabetes in Japan." (PMID 30226870, 2018). "A clear dose-response relationship can be demonstrated for both insulin analogs, even at very high doses in severely obese patients with type 2 diabetes." (PMID 30114246, 2018). "Type 1 diabetes results from inadequate synthesis of insulin by pancreatic β-cells, while type 2 diabetes is characterized primarily by insulin resistance or β-cell dysfunction." (PMID 30003087, 2018). "The MiTy Kids trial will assess the children of mothers with type 2 diabetes receiving metformin in addition to insulin." (PMID 29973490, 2018). "It has also been shown that exercise training in type 2 diabetic rats improved insulin-stimulated glucose transport in skeletal muscle." (PMID 29920546, 2018). "Type 2 diabetes generally develops as a consequence of the imbalance between insulin resistance and insulin secretion." (PMID 30041479, 2018). "Yet, the main finding of our study is that BCAAs predicted incident type 2 diabetes even when taking into account insulin resistance and β cell function." (PMID 30518023, 2018). "A 16-week treatment of PIO significantly increased insulin sensitivity, first phase insulin secretion, and β-cell glucose sensitivity in the Chinese type 2 diabetes patients." (PMID 29536426, 2018). "In contrast to type 1 diabetes patients who need insulin injections, many type 2 diabetes patients require only oral medications in addition to self-care activities." (PMID 30123316, 2018). "Christiansen JS, Niskanen L, Rasmussen S, Johansen T, Fulcher G. Lower rates of hypoglycemia during maintenance treatment with insulin degludec/insulin aspart versus biphasic insulin aspart 30: a combined analysis of two Phase 3a studies in type 2 diabetes." (PMID 29527102, 2018).
type 2 diabetes (continued). "Exercise improves insulin secretion by pancreatic beta cells (β-cells) in patients with type 2 diabetes, but molecular mechanisms of this effect are yet to be determined." (PMID 29966345, 2018). "Edridge CL, Dunkley AJ, Bodicoat DH, Rose TC, Gray LJ, Davies MJ, Khunti K. Prevalence and incidence of hypoglycaemia in 532,542 people with type 2 diabetes on oral therapies and insulin: a systematic review and meta-analysis of population based studies." (PMID 29527102, 2018). "In this study, patients with type 2 diabetes attending a tertiary care referral centre showed inadequate adherence to insulin therapy." (PMID 30116737, 2018). "Also, risk of type 2 diabetes is higher in certain ethnic groups Impaired glucose metabolism in type 1 diabetes is due to the complete destruction of beta cells, while in the case of type 2 diabetes, this phenomenon arises due to insulin resistance and beta cell dysfunction." (PMID 30044774, 2018). "The expression of CD36 is upregulated by insulin, and the expression in adipose tissue is also upregulated in obesity and in type 2 diabetes patients." (PMID 29075849, 2018). "Hypoglycemia remains the greatest barrier to achieving and maintaining tight glycemic control in people with type 1 diabetes and people with type 2 diabetes on insulin therapy or sulfonylurea treatment." (PMID 29347915, 2018). "Twenty-seven patients with type 2 diabetes (T2D) were treated with oral hypoglycemic agents, glucagon-like peptide-1 receptor agonist, or insulin." (PMID 30214502, 2018). "Garber AJ, Clauson P, Pedersen CB, Kølendorf K. Lower risk of hypoglycemia with insulin detemir than with neutral protamine hagedorn insulin in older persons with type 2 diabetes: a pooled analysis of phase III trials." (PMID 29527102, 2018). "By contrast, Hellmuth and colleagues (2000) reported increased perinatal mortality and preeclampsia in a retrospective study of 50 women with type 2 diabetes taking metformin compared with those treated with sulphonylureas or insulin." (PMID 29973490, 2018). "Hypoglycaemia is also an issue in insulin-treated type 2 diabetes, but the use of technology to prevent hypoglycaemia in this group has not been studied in detail." (PMID 29423581, 2018). "The higher level of plasma insulin required for maintaining the normal glucose levels actually is the earliest sign of the onset of type-2 diabetes in HFHS-rats and it is in agreement with our previous results." (PMID 30261666, 2018). "For type 2 diabetes, hypertriglyceridemia is the most common type of dyslipidemia, which is mainly induced by IR and impairment in insulin secretion." (PMID 30110382, 2018). "External insulin administration is mandatory for people with type 1 diabetes; various medications, as well as basal and prandial insulin, are included in the daily treatment of type 2 diabetes." (PMID 32232090, 2018). "In times of famine, starving people rarely suffer from obesity and type 2 diabetes despite insufficient energy intake diminishes insulin production and the energy expenditure to avert hypoglycemia." (PMID 30275974, 2018). "We anticipate that this reporter used in combination with the human insulin promoter will represent a powerful tool to address various issues regarding ER stress in beta cells in type 1 diabetes as well as type 2 diabetes." (PMID 30532033, 2018). "In fact, mounting knowledge has suggested a common molecular defect linking type 2 diabetes and Alzheimer’s Disease, which resulted in defective insulin signaling and chronic inflammation in the brain tissue." (PMID 29579115, 2018). "In some animal models, a decrease in adiponectin level was found to parallel to a reduction in insulin sensitivity and to precede the onset of type 2 diabetes." (PMID 29472867, 2018). "The relationship between AT SIRT1 and indirect indices of insulin sensitivity and the values from the clamp study in subjects with a family history of type 2 diabetes was also observed by other researchers." (PMID 29417372, 2018).